ABCG2 (ATP binding cassette subfamily G member 2 (JR blood group))
Diseases named in the same sentence as ABCG2 in open-access papers (continued):
Sharing a sentence is not in itself a finding about the gene and the disease.
cancer (continued). "ABCG2 gene amplification plays an important role in ABCG2 overexpression in MDR cancer cells." (PMID 33066132, 2020). "Our findings provide evidence that venetoclax in combination therapy may be a beneficial strategy to overcome wild-type ABCG2-mediated cancer MDR." (PMID 32085398, 2020). "Taken together, our studies indicate that AZ-628 could be used in combination chemotherapy against ABCG2-mediated MDR in cancers." (PMID 33364237, 2020). "ABC transporters including ABCB1, ABCC1, and ABCG2 are expressed in cancer stem/progenitor cells." (PMID 32582535, 2020). "ABCB1 gene polymorphism and ABCG2 upregulation may be responsible for the resistance of NPC cancer stem cells to chemotherapeutic drugs; tumour suppressor gene IRF6 kills cancer stem cells in NPC by targeting the ABCG2 gene." (PMID 32595725, 2020). "In addition to its crucial defense role in normal tissues, ABCG2 is also involved in multidrug resistance in cancer cells." (PMID 31254042, 2020). "Several reports have demonstrated that in addition to inhibiting the drug efflux function of ABCB1 and ABCG2, the transient down-regulation of these transporters is one of the common alternative mechanisms in which the multidrug-resistant cancer cells can be re-sensitized to chemotherapy." (PMID 31941029, 2020). "Moreover, due to a trace amount of ABCG2 protein expressed in H460 cancer cells, we and others have observed evidence of chemosensitization in H460 cells by sitravatinib and other strong modulators of ABCG2." (PMID 31941029, 2020). "Therefore, we first examined the cytotoxicity of erdafitinib in multiple human multidrug-resistant cancer cell lines that overexpress ABCB1 or ABCG2 as well as in the corresponding drug-sensitive parental cancer cell lines." (PMID 32466597, 2020). "Similarly, 5 μM of sitravatinib also increases the accumulation of pheophorbide A (PhA), a fluorescent substrate of ABCG2, in ABCG2-transfected R482-HEK293 cells and ABCG2-overexpressing S1-M1-80 cancer cells." (PMID 31941029, 2020). "Therefore, in this study, we determined the efficacy of MCA in ABCB1- and ABCG2-overexpressing cancer cells and in HEK293 cells transfected with either ABCB1 or ABCG2 cDNA." (PMID 32676451, 2020). "The induction of ABCG2 mRNA in primary hepatocytes is also observed; however, the magnitude of induction is relatively small in human hepatocytes compared with those of the human carcinoma cell lines, which suggests a cell-dependent induction." (PMID 33551819, 2020). "Moreover, we observed that inhibition of 5-Lox downregulates CD44, CD133, ALDH1 and ABCG2 which are characterized to be cancer stem cell- or tumorigenicity-markers in adult stem cells." (PMID 30728896, 2019). "PEPT1 was upregulated and ABCG2 downregulated in cancer cells treated with cisplatin." (PMID 31426474, 2019). "Also, ABCG2 is found to be particularly overexpressed in a subpopulation of slow-cycling cancer stem-like cells with self-renewal capacity and high chemoresistance." (PMID 31814840, 2019). "Our results indicate that the overexpression of ABCB1 or ABCG2 is unlikely to reduce the susceptibility of cancer cells to TMP195." (PMID 31905792, 2019). "The inhibitory effect of TMP195 on ABCB1- and ABCG2-mediated drug transport, as well as its effect on the protein expression of ABCB1 and ABCG2 in multidrug-resistant cancer cells were examined to elucidate the potential mechanism(s) of chemosensitization by TMP195." (PMID 31905792, 2019). "Among these transmembrane proteins, the cellular protein P-glycoprotein (P-gP/MDR1/ABCB1), the multidrug resistance proteins (MRPs), and the breast cancer resistance protein (BCRP/ABCG2) mediate classic multidrug resistance (MDR) in cancer cells by functioning as an energy-driven efflux pump." (PMID 31487863, 2019). "ABCG2 is responsible for the transport of several cancer therapeutic drugs." (PMID 35582590, 2019).
cancer (continued). "To evaluate whether the increased expression of ABCG2 could resist the cytotoxicity of anti-cancer drugs, we observed the level of efflux capacity of the colonies using verapamil as the ABC transporter inhibitor." (PMID 31727938, 2019). "In addition, the ABCG2 gene, also known as the breast cancer resistance protein (BCRP), is responsible for the transport of many conventional chemotherapeutics and causes MDR in various cancer cells." (PMID 31391850, 2019). "ABCG2 (breast cancer resistance protein, BCRP) transports various endogenous and exogenous chemicals, thereby mediating drug resistance and affecting the pharmacological action of many compounds in different drug-resistant cancer cells." (PMID 31083682, 2019). "ABCG2 is not only expressed by cancer cells, but also by small intestinal epithelial cells, renal proximal tubule epithelial cells, liver cells, and capillary endothelial cells in the brain, and it influences the pharmacokinetics of drugs that are its substrates." (PMID 31340525, 2019). "ABCB1 and ABCG2 when overexpressed, transport chemotherapeutic drugs out of cancer cell." (PMID 31570733, 2019). "Notably, several studies demonstrated that drug-induced transient downregulation of ABCB1 or ABCG2 is another common mechanism in which the multidrug-resistant cancer cells can become resensitized to chemotherapeutic drugs." (PMID 31905792, 2019). "ABCG2 is a key protein in the extrusion of endo- and xenobiotics from numerous cell types and was shown to be involved in uric acid secretion, the modulation of drug absorption, as well as in the drug resistance of cancer cells." (PMID 31597297, 2019). "Therefore, cancers overexpressing ABCG2 would readily excrete these anticancer agents, reducing intracellular drug concentrations and possibly decreasing their antitumor activity." (PMID 31340525, 2019). "Thereafter, many studies were conducted to determine the role of ABCG2 in developing MDR in cancer." (PMID 30890942, 2019). "An elevated expression level of ABCG2 in the cancer cells can be closely associated with the difficulty in 5‐ALA–based discrimination between cancer (MCF7, MDA‐MB‐231) and noncancer (MCF10A) cell lines in flow cytometry." (PMID 31385432, 2019). "Our findings indicate that Y6 may potentially be a novel reversal agent in ABCG2-positive drug-resistant cancers." (PMID 30687102, 2018). "Furthermore, reduced ATPase activity, mRNA transcription, and protein expression levels of ABCB1 and ABCG2 were observed in a concentration dependent manner in MDR cancer cells." (PMID 30544754, 2018). "LS-2-3j might be useful as a lead compound in drug discovery and development for ABCB1- or ABCG2-mediated MDR cancer treatment." (PMID 30544754, 2018). "Our results, provided they can be extended to humans, suggest that cariprazine could be used in combination with FDA approved anticancer drugs, which are ABCG2 substrates, to increase the likelihood of overcoming cancers that overexpress ABCG2 transporters." (PMID 30181510, 2018). "It indicated that combination of VS-4718 with antineoplastic drugs could attenuate MDR mediated by ABCB1 or ABCG2 in ABCB1- or ABCG2-overexpressing cancer cells." (PMID 30425643, 2018). "The combination of VS-4718 with substrate drugs of ABCB1 and ABCG2 transporters might be used for cancer clinical treatment to elude MDR if it could be validated in in vivo models." (PMID 30425643, 2018). "The major ABC transporters responsible for resistance to anti-cancer chemotherapeutics include MDR-1 (P-glycoprotein) encoded by the human ABCB1 gene located on chromosome 7q21 and Breast Cancer Resistance Protein (BCRP) encoded by the human ABCG2 gene located on chromosome 4q22." (PMID 30460040, 2018).
cancer (continued). "Previous studies have shown that the expression of the ABCG2 protein in various cancer cell lines is mediated by the activation of c-jun N-terminal kinase, mitogen-activated protein kinases, phosphate and tensin homolog, epidermal growth factor receptor and human epidermal growth factor (EGFR)." (PMID 30181510, 2018). "Our study provides a clue that the combination of VS-4718 with ABCB1 or ABCG2 substrate-drugs, like doxorubicin or topotecan, as well as SN-38, could be a novel treatment strategy to antagonize resistance in cancer patients." (PMID 30425643, 2018). "Studies have found that one of the mechanisms of MDR is the overexpression of ATP-binding cassette (ABC) superfamily of transporters in cancer cells, such as P-glycoprotein (P-gp/ABCB1), MDR-associated protein 2 (MRP2/ABCC2), and breast cancer resistance protein (BCRP/ABCG2)." (PMID 29334793, 2018). "Interestingly, it has been demonstrated that the PI3K/Akt pathway specifically regulates ABCG2 activity via its localization to the plasma membrane, and loss of PTEN promotes the SP phenotype of human glioma cancer stem-like cells." (PMID 29681949, 2018). "Dacomitinib may be adopted as a novel chemosensitizer to overcome MDR in ABCG2-overexpressing cancer cells." (PMID 29458405, 2018). "ABCG2 is characterized as a part of self-defense systems and function as an efflux pump to transfer the toxic endogenous molecules and xenobiotics, including many cancer chemotherapies, out of the cell." (PMID 30687102, 2018). "Moreover, FOXC1 knockdown decreased expression of Oct4, NANOG, SOX2 and ABCG2, which are important downstream target genes of beta-catenin in regulating cancer stemness." (PMID 30189871, 2018). "Considering that ABCG2 is a major ABC transporter in cancer stem cells and its pump function is dependent on ATP5,6, we tested if AF could affect cellular ATP and thus impact the function of ABCG2 transporter." (PMID 29367724, 2018). "AhR promotes the cancer stem-like phenotype and drives metastasis by directly targeting the promoters of ‘stemness’ genes, such as the ATP-binding cassette sub-family G member 2 (ABCG2) gene." (PMID 29706625, 2018). "In addition, miR-328 regulates the expression of breast cancer resistance protein (BCRP/ABCG2) in human cancer cells, resulting in increased chemosensitivity." (PMID 29374351, 2018). "Later on, it was understood that MDR1/P-gp alone cannot be responsible for every type of MDR and this eventually led to the discovery of other related transporters, especially breast cancer–resistance protein (BCRP, also known as ABCG2) and MDR-associated protein (MRP1 also known as ABCC1)." (PMID 28587082, 2017). "Simultaneous expression of PEPT1 and ABCG2 genes could have a pivotal role in PpIX accumulation in cancer tissues." (PMID 28257041, 2017). "We hypothesized that interaction between cancer cells expressing VCAM-1 and macrophages expressing VLA-4 might induce expression of ABCG2 in the cancer cells." (PMID 28969049, 2017). "Among these, Ko143, a highly potent analogue of fumetremorgin C1, has been shown to re-sensitize human cancer cell lines with acquired SN-38 resistance and significant upregulation of ABCG2 mRNA as well as to enhance the efficacy of irinotecan in ABCG2-expressing CRC xenograft tumor models." (PMID 28880238, 2017). "Therefore, our study demonstrated that DMC induced oxidative stress in cancer cells and ABCG2 overexpression decreased ROS, thereby reducing the efficacy of DMC in GSCs." (PMID 28591733, 2017). "Furthermore, we demonstrated that inhibition of ABCG2 by expressing a truncated ABCG2 molecule or addition of a specific inhibitor, sensitizes cancer cells to CDDP treatment." (PMID 28404967, 2017). "We investigated ABCG2 expression in the cancer cell components of the co-culture systems." (PMID 28969049, 2017). "LPS stimulation increased ABCG2 expression in 4T1 cancer cells." (PMID 28969049, 2017).
cancer (continued). "Furthermore, a study of normal tissue and matched primary tumors from 13 CRC patients showed that the ABCG2 mRNA was decreased six-fold in cancer tissue compared to matched normal CRC mucosa." (PMID 28880238, 2017). "ABCG2 transports a wide variety of substrates including several anticancer agents and is one of the most significant contributors to multidrug resistance in cancer cells." (PMID 28347288, 2017). "Recent studies have shown that ABCG2 has a vital role in the multidrug resistance of cancer cells and may influence the overall survival of tumor patients." (PMID 28347288, 2017). "Moreover, CBP501 suppressed expression of ABCG2, a marker for CSCs, by inhibiting the interaction between cancer cells expressing VCAM-1 and macrophages expressing VLA-4." (PMID 28969049, 2017). "CD44, ABCG2, Oct3/4, Nanog are frequently used as makers for cancer stem cells." (PMID 28076853, 2017). "In contrast, administration of CBP501 suppressed ABCG2 expression in the cancer cells." (PMID 28969049, 2017). "Our results indicate that CBP501 suppresses the ABCG2 expression on cancer cell surfaces that may be induced in a co-culture system upon stimulation with LPS or HMGB1." (PMID 28969049, 2017). "However, ATP-binding cassette sub-family G member 2 (ABCG2) and OCT-4 (also known as POU5F1 (POU family of transcription factors, class 5, factor 1)) are accepted CSC markers in numerous cancers and are linked with prognosis." (PMID 28212529, 2017). "Taken together, these results show that CBP501 can suppress ABCG2 expression in cancer cells by suppressing cell-cell interactions between cancer cells expressing VCAM-1 and macrophages expressing VLA-4, at least by reducing the expression levels of these surface molecules." (PMID 28969049, 2017). "CBP501 might therefore suppress ABCG2 expression on cancer cells not only through reduction of expression levels of VCAM-1 and β1-integrin, but also through its suppression of integrin function." (PMID 28969049, 2017). "The expression of previously-reported candidate marker genes, such as CD133, CD44 and ABCG2, which are argued to be related to cancer stem cells, and the transduced genes OCT3/4, SOX2 and KLF4 were not significantly different among the parental A549, OSK-A549-Colony and OSK-A549-SN cells." (PMID 28951614, 2017). "ABCG2 is highly expressed in cancer stem cells or side-population cells and may protect the cells by pumping out xenobiotics, detrimental metabolites of oxidative stress, and chemotherapeutic drugs." (PMID 28347288, 2017). "As ABCG2 has a low substrate specificity, it might contribute to the resistance to structurally diverse anti-cancer drugs, a phenomenon called multidrug resistance (MDR)." (PMID 26578453, 2016). "ABCG2 often lowers the bioavailability of other drugs such as rosuvastatin, which is widely used to treat dyslipidemia, and sunitinib, a multi-targeted receptor tyrosine kinase inhibitor used in cancer chemotherapy." (PMID 28082903, 2016). "Overexpression of the ATP-dependent drug efflux pump ABCG2 is a major molecular mechanism of multidrug resistance in cancer and might be a predictive biomarker for drug response." (PMID 27257141, 2016). "Considering that ABCG2 is expressed in cancer cells, febuxostat might enhance the efficacies of PDT/PDD by accumulating photosensitizers in the target cells." (PMID 28082903, 2016). "These spheroids, that represent a validated and widely used method to study cancer stem cells in vitro, are enriched in cells with stem-like phenotype, expressing CD133, ABCG-2, Oct-4, Sox-2 that are directly associated with stemness features and tumor formation in vivo." (PMID 27367907, 2016). "Increasing evidence suggests that ABCG2 is involved in MDR of cancer stem cells." (PMID 27689338, 2016). "Thus, we determined the promoter methylation patterns of ABCB1, ABCC1 and ABCG2 in 19 human cancer cell lines." (PMID 27689338, 2016).
cancer (continued). "Since ABCG2 is one of the genes responsible for the development of MDR in cancer cells, the inhibition of ABCG2 could enhance the efficacy of chemotherapy, leading to an efficient accumulation of anticancer agents." (PMID 28082903, 2016). "With preclinical data demonstrating the functional involvement of ABCG2 in resistance to several anti-cancer drugs, studies should now be undertaken to clinically investigate ABCG2 as a predictive biomarker, including validation of the proposed scoring protocol." (PMID 27257141, 2016). "ABCG2/BCRP is a membrane protein, involved in xenobiotic and endobiotic transport in key pharmacological barriers and drug metabolizing organs, in the protection of stem cells, and in multidrug resistance of cancer." (PMID 27741279, 2016). "Diestra and colleagues have investigated ABCG2 expression in different cancers including CRC." (PMID 27257141, 2016). "Moreover, the average methylation status of the ABCG2 promoter (across the eight CpGs in the sequence to analyze) was even < LOQ in five cancer cell lines (A2780, KB-3-1, MDA-MB-231, HCT116 and U266)." (PMID 27689338, 2016). "ATP-binding cassette subfamily G member 2 (ABCG2) is a member of the ABC transporter superfamily proteins, which has been implicated in the development of multidrug resistance (MDR) in cancer, apart from its physiological role to remove toxic substances out of the cells." (PMID 26515463, 2015). "Pazopanib could itself be a substrate of ABCG2 and thus mediates a pharmacodynamic interaction with LDM topotecan, resulting in a competitive inhibitory mechanism at the level of topotecan extrusion from the cancer cell mediated by ABCG2." (PMID 26623560, 2015). "The silencing of ABCG2 using small interfering RNA (siRNA) could be a promising approach to overcome multidrug resistance (MDR) in cancer cells." (PMID 26575421, 2015). "The high expression of components of the HIF-2α-ABCG2 pathway leads to MDR in cancer stem cells." (PMID 25452783, 2015). "Our findings indicate that a combination of A-803467 and ABCG2 substrates may potentially be a novel therapeutic treatment in ABCG2-positive drug resistant cancers." (PMID 26515463, 2015). "In addition, ABCG2 expression is a distinguishing feature of cancer stem cells, whereby this membrane transporter facilitates resistance to the chemotherapeutic drugs." (PMID 26515463, 2015). "ABCG2 mRNA levels in unaffected tissue from cancer patients were higher than the level in tissue from healthy individuals, but considerable variation was observed, and the difference was only statistically significant for adjacent unaffected tissue (p = 0.011)." (PMID 25793771, 2015). "Thus, we here investigated the effects of ABCG2 expression on the anti-cancer effects of tozasertib and alisertib." (PMID 26415506, 2015). "Since ABCG2 was first identified in drug-resistant cancer cells, it was hypothesized that a variety of cytotoxic agents were substrates for ABCG2, and that resistance to these agents was the result of drug efflux by ABCG2." (PMID 26714461, 2015). "Thus, targeting ABCG2 in the tumor stem cells represents a promising and novel strategy to eradicate the entire cancer cell population." (PMID 26556876, 2015). "Importantly, BORIS-silencing led to down-regulation of hTERT, stem cell (NANOG, OCT4, SOX2 and BMI1) and cancer stem cell markers (ABCG2, CD44 and ALDH1) genes." (PMID 26185996, 2015). "Moreover, ABCB1 and ABCG2 are frequently found highly expressed on cancer cells playing an important role in cancer cell chemoresistance." (PMID 25749379, 2015). "This chemoresistance may be associated with the high expression of cancer stem cell markers HIF-2α, ABCG2 and Oct-4 and tumor stem cell promotion." (PMID 25452783, 2015). "Among them, ABCB1, ABCC1, and ABCG2 play major roles in the development of MDR in cancer cells." (PMID 26506420, 2015).